GSN (gelsolin)
Diseases named in the same sentence as GSN in open-access papers (continued):
Sharing a sentence is not in itself a finding about the gene and the disease.
tumor (continued). "In addition, several molecules associated with tumor mechanisms and related to tumor immune responses such as gelsolin, periostin, osteopontin, lumican and vitamin D, were identified in the PC secretome dependent on GB-induced CMA." (PMID 35419364, 2022). "It remains unclear whether the increased or decreased expression of gelsolin is associated with adverse prognosis in human neoplasms, which is possibly due to the nuanced and multifactorial nature of tumorigenesis." (PMID 34144901, 2022). "Statistical results showed that gelsolin expression in PCa was associated with disease status, tumor grade, cigarette smoking, serum PSA level, lymphovascular infiltration and the expression of androgen receptor, AKR1C2 and epidermal growth factor receptor (EGFR)." (PMID 29100377, 2017). "Previous studies have showed that GSN might affect the migration and invasion ability of tumour cells through governing the dynamic changes of the cytoskeleton in tumour cells, and GSN knockdown would cause severe DNA damage and promote apoptosis following radiotherapy." (PMID 40375605, 2025). "Importantly, GSN expression was reported to be positively associated with anti-tumor immunity." (PMID 39261905, 2024). "Therefore, we hypothesize that the FN1, CTSD, and GSN interaction is associated with cell adhesion and metastasis in tumor cells." (PMID 26056562, 2015). "Gelsolin plays a multifaceted role in cancer, operating as a tumor suppressor and promoter depending on the situation." (PMID 40723199, 2025). "Collectively, these findings identify GSN as a multifunctional regulator in CC—suppressed in tumor tissues but exploited by HPV16 E7 to promote actin remodeling, EMT, and oncogenic signaling." (PMID 41148856, 2025). "Silencing UHRF1 increased GSN expression, induced cell-cycle arrest, and promoted apoptosis, suggesting that GSN suppression via the USP7–UHRF1 axis supports tumor progression." (PMID 41148856, 2025). "Injection with AAV‐GSN into subcutaneous tumours effectively upregulated GSN mRNA expression in mouse tumour tissues." (PMID 40375605, 2025). "GSN was found to be overexpressed in HCC tissues and correlated with advanced tumor grade and poor prognosis, while GSN knockdown inhibited tumor cell migration and invasion and GSN overexpression had the opposite effect." (PMID 39061201, 2024). "The tumour size in the GSN‐KD group was smaller than that in the NC group, suggesting that GSN‐KD strengthened the effect of radiation on tumour suppression in vivo." (PMID 38803199, 2024). "Current evidence indicates that gelsolin can serve as either an oncoprotein or a tumor suppressor, contingent upon the specific carcinoma type." (PMID 39000458, 2024). "A dual role of gelsolin as tumor suppressor and oncogene has been observed in different human cancers." (PMID 38216951, 2024). "GSN expression is down‐regulated in 60%–90% of tumours during carcinogenesis in the breast, colon, stomach, bladder, prostate and lungs." (PMID 38803199, 2024). "Cancer immune evasion can occur through tumor-derived prostaglandin E2 (PGE2) that impairs cDC1 function as well as tumor-secreted gelsolin that reduces CLEC9A binding to dead cell fragments, thus affecting cDC1-mediated cross-presentation." (PMID 37907944, 2023). "Of great significance for cancer, gelsolin is essential for anti-tumor immune cell infiltration (we refer the interested reader to a recent review)." (PMID 37373424, 2023). "Lastly, the GSN gene was also analyzed by comparing and identifying common co-expressed genes among healthy tissue, adjacent healthy tissue, and tumor tissue groups." (PMID 37365287, 2023).
tumor (continued). "The alteration of GSN results in altered actin cytoskeletal architecture and increased cell motility, both of which are essential for tumor cellular migration and invasive growth." (PMID 36192574, 2023). "Herein, the correlation between GSN expression in different tumor stages was found that in tumors with decreased GSN expression, including BLCA, THCA and SKCM, the decrease in GSN expression was more significant in early cancers." (PMID 37035750, 2023). "A model consisting of four predictors (FIGO stage, residual tumor after surgery, and plasma levels of GSN and VCAN) showed the best predictive performance (mean validated AUC, 0.779)." (PMID 36669591, 2023). "In the present study, we demonstrate that HBP1 can be methylated by PRMT1 at R378, which alleviates HBP1-mediated repression of tumor metastasis and growth through regulation of GSN expression." (PMID 35941115, 2022). "By contrast, GB-induced CMA in PCs induces a secretome with high levels of proteins that can promote tumor angiogenesis and facilitate pro-tumor immune responses (e.g., angiotensin, gelsolin, periostin, and osteopontin)." (PMID 36012149, 2022). "We demonstrated that p54nrb dependent regulation of cathepsin-Z and gelsolin was universal across all the three tumor cell lines investigated." (PMID 35444189, 2022). "Methylation of HBP1 promotes actin cytoskeleton remodeling, glycolysis and tumor progression by downregulating GSN (a vital actin-binding protein) levels." (PMID 35941115, 2022). "To further determine the role of GSN in the metastasis and growth of tumor cells, we established two stably transfected cell lines with lower GSN expression using lentiviral vectors expressing a GSN-targeting shRNA, designated as shGSN-1 and shGSN-2." (PMID 35941115, 2022). "Methylated HBP1 can decrease protein stability by promoting its ubiquitination and proteasome-mediated degradation, thereby reducing GSN expression and promoting actin cytoskeleton remodeling and tumor progression." (PMID 35941115, 2022). "Although gelsolin can apparently have opposite actions depending on tumor type, detailed analysis of its expression status in different tumor sites are crucial for understanding its impact on carcinogenesis." (PMID 34144901, 2022). "Overall, our data suggest that GSN acts as a growth inhibitor in these cell lines, and is involved in actin cytoskeleton remodeling in tumor cells." (PMID 35941115, 2022). "The expression of GSN on the membrane of tumor cells is generally accompanied by lymph node metastasis." (PMID 36338135, 2022). "Accordingly, the loss of GSN and PRDX4 increases susceptibility to oxidative stress and tumor aggression and requires further study." (PMID 35804959, 2022). "Some of the previously conducted studies suggest the role of inhibiting Gelsolin gene in tumor suppression." (PMID 33391377, 2021). "In this context, secreted gelsolin has been shown to inhibit neoantigen presentation to conventional dendritic cells in the tumor microenvironment, leading to immune evasion with a subsequent increase in glutathione (GSH) expression." (PMID 34948433, 2021). "As GSN is further widely debated as biomarker candidate in different cancers with evidence supporting its contradictory involvement in both tumor suppression as well as malignant progression, the reported data stress the need for strict SOPs research." (PMID 32408476, 2020). "GSN is a ubiquitous actin filament-severing protein, whose tumor-suppressive functions on various cancer types when highly expressed were previously noted." (PMID 33014872, 2020). "Subsequently, the protein levels of LAMC2 and GSN were respectively down-regulated and up-regulated in tumor tissue with the Human Protein Atlas (HPA) database." (PMID 32640634, 2020). "In this study, significant down-regulation of Gelsolin (p=0.001) and over-expression of Scinderin (p=0.001) were observed in tumor tissues compared to the adjacent normal tissues." (PMID 32636728, 2020).
tumor (continued). "GSN was initially recognized as a tumour suppressor and is downregulated in certain types of cancer, including human breast, colorectal, gastric, bladder, and non-small-cell lung cancers." (PMID 32377190, 2020). "On the other hand, the protein expression of GSN was moderately higher in tumor tissues than normal." (PMID 32640634, 2020). "According to the literature, the abnormal splicing level of the GSN gene is remarkably higher in tumor tissues than in para-carcinoma tissues and regulates the proliferation process of the HNSCC cell line." (PMID 32117741, 2020). "Further experiments will be necessary to analyze the functional role of the interaction between cortactin and gelsolin in tumor progression of PDAC." (PMID 30976201, 2019). "In vitro studies revealed that the transfection of gelsolin into HGSOC cells inhibited colony formation, suggesting a tumor-suppressive effect of gelsolin." (PMID 30149613, 2018). "We identified novel XAV939-induced proteins, including gelsolin (a possible tumor suppressor) and lactate dehydrogenase A (a key enzyme of glycolysis), which were differentially expressed between 2D- and 3D-cultured SW480 cells." (PMID 30185973, 2018). "GSN immunoreactivity was more prominent at the invasive front than in the central tumor in approximately 1/3 of tissue samples, indicating individual susceptibility to GSN-mediated invasion." (PMID 30148861, 2018). "Gelsolin expression also correlated with disease status and tumor grade of American PCa patients as well." (PMID 29100377, 2017). "In cancer, GSN has a dual effect as a promoter of cell growth and invasion and as a tumor suppressor that inhibits metastasis." (PMID 28542306, 2017). "Taken together, these data implicate the role of intracellular O2.- in gelsolin-induced tumor cell invasion and uPA secretion." (PMID 27391159, 2016). "High expression of Gelsolin (GSN) correlates with tumor size, advanced Enneking stage, and poor prognosis in OS patients." (PMID 27888627, 2016). "This is corroborated by previous reports that gelsolin is required for tumor cell invasion and cellular aggregation in various carcinomas." (PMID 27058427, 2016). "Several in vivo and in vitro studies have indicated that gelsolin is crucial for the migration and invasion of tumor cells." (PMID 27419625, 2016). "The evidence is also concordant with data showing higher gelsolin levels in cell lines derived from metastatic sites, as well as a previous reports documenting increased gelsolin expression in tumor metastases." (PMID 27058427, 2016). "GSN knockdown decreased cell viability and tumor cell invasion, whereas GSN overexpression correlates with proliferative and invasive capacities." (PMID 27846905, 2016). "Taken together, these findings provide insight into a novel function of gelsolin in promoting tumor invasion by directly impacting the cellular redox milieu." (PMID 27391159, 2016). "Since gelsolin probably plays a significant role in cell transformation into tumor cells, it is likely to have a role during embryonic development, because in both situations cells detach, migrate/invade and colonize new environments." (PMID 25352156, 2016). "Together with the notion that gelsolin is a tumor suppressor, it suggests gelsolin’s role in NC cells development can have other implications, than simply regulating the actin cytoskeleton and thus influencing cell motility." (PMID 25352156, 2016). "Conversely, a number of studies have shown the tumorigenic potential of gelsolin, including our report on gelsolin's role in inducing uPA secretion to promote tumor cell invasion." (PMID 27391159, 2016). "In vitro, human gelsolin has anti-apoptotic and pro-migratory functions and is critical for invasion of some types of tumor cells." (PMID 24367717, 2013). "We found that gelsolin was highly expressed at tumor borders infiltrating into adjacent liver tissues." (PMID 24367717, 2013).
tumor (continued). "Gelsolin appears to have complex roles in tumor biology, with evidence supporting its contradictory involvement in both tumor suppression as well as malignant progression." (PMID 22927998, 2012). "Gelsolin has previously been shown to be important for migration of fibroblasts and invasion of other tumor cells, attributable partly to its actin-depolymerizing effects." (PMID 22927998, 2012). "Although gelsolin contributes to lamellipodia formation in migrating cells, the mechanisms by which it induces tumor invasion are unclear." (PMID 22927998, 2012). "We found that gelsolin was highly expressed at tumor borders infiltrating into adjacent liver tissues, as examined by immunohistochemistry." (PMID 22927998, 2012). "Although initially regarded as a tumor suppressor, gelsolin expression in certain tumors correlates with poor prognosis and therapy-resistance." (PMID 22927998, 2012). "Immunohistochemical (IHC) analysis showed prominent gelsolin expression along the tumor borders of both primary human colon tumors and liver metastases." (PMID 22927998, 2012). "We found gelsolin expression to be heterogeneously expressed in the matched primary tumors and liver metastases, with regions of low and high expression seen within a tumor." (PMID 22927998, 2012). "In liver metastases, gelsolin expression was significantly higher in the tumor borders compared to the main tumor bulk (p = 0.0075, Mann-Whitney test)." (PMID 22927998, 2012). "Increased gelsolin expression was found to correlate with lymphatic invasion in small cell lung cancer and higher tumor grade in renal cell carcinoma." (PMID 22927998, 2012). "In vitro, gelsolin has anti-apoptotic and pro-migratory functions and is critical for invasion of some types of tumor cells." (PMID 22927998, 2012). "We therefore analyzed the pattern of gelsolin expression at the tumor borders compared to the tumor bulk, as these populations are potentially disseminative." (PMID 22927998, 2012). "Alterations of other proteins that are supposed to function as tumour suppressors and oncoproteins were detected (14-3-3 proteins, RhoGDI2 protein, TEF1δ, DJ-1, Gelsolin and hnRNP H1)." (PMID 19367286, 2009). "Further biological researches on gelsolin will certainly be required in order to exploit the tumour-suppressing effect of gelsolin expression in the clinical field." (PMID 12592377, 2003). "It was suggested that gelsolin suppressed tumour growth in vivo by affecting the cell-proliferating ability of PC10 rather than by inducing apoptosis." (PMID 12592377, 2003). "Consequently, clinicopathological characteristics and the expression levels of GSN, SCIN, CAPG, VILL, VIL1, SVIL, and FLII were found to be closely associated with tumor stages in EC." (PMID 39964147, 2025). "Moreover, gelsolin contributes to wound repair, epithelial-to-mesenchymal transition, and tumor cell invasion." (PMID 40106086, 2025). "In certain situations, gelsolin can promote apoptosis and act as a tumor suppressor in cancer." (PMID 40723199, 2025). "On the other hand, cisplatin-resistant tumor cells induce apoptosis of CTLs by secreting plasma gelsolin (pGSN) and exosome-a type of small extracellular vesicle (sEV), which leads to a decrease in IFN-γ secretion and renders the tumor cells resistant to cisplatin-induced apoptosis." (PMID 39757995, 2025). "Additionally, tumor-associated macrophages increase DNMT1 expression in gastric cancer cells, leading to the silencing of the tumor-suppressing gelsolin gene." (PMID 38988323, 2024). "The tumour size in the GSN‐KD group was smaller than that in the NC group after RT in vivo." (PMID 38803199, 2024).
tumor (continued). "Corroborating our finding, Van den Abbeele and colleagues (2007) demonstrated that the downregulation of gelsolin in several cancer cell types significantly reduces the invasive and motile properties of the cells, as well as cell aggregation, pointing to a role for gelsolin as tumor activator." (PMID 39061201, 2024). "According to our results, GSN could regulate cancer immunity, and targeting GSN might become a new strategy for tumor immunotherapy." (PMID 37035750, 2023). "Additionally, it was revealed that specific tumor cells had lower cellular levels of GSN and that overexpressing GSN by gene transfer reduces tumorigenicity." (PMID 37970212, 2023). "Interestingly, this apparent dis-regulation of GSN expression has been previously reported by different studies where GSN has been suggested serve as either a tumor suppressor or tumor activator depending on the tumor type and tumor stage." (PMID 37958747, 2023). "Serum gelsolin showed varying impacts on tumor type prognosis." (PMID 37373424, 2023). "We also screened an important cellular target of the nicotine metabolite cotinine, gelsolin, which may affect basic tumour transformation and metastasis processes, such as migration and apoptosis, through gelatine." (PMID 37753171, 2023). "Furthermore, we examined the link between GSN expression levels and various tumor immunological cell infiltration utilizing EPIC, MCP-COUNTER, CIBERSORT, and TIDE algorithms through the Timer2.0 database." (PMID 37035750, 2023). "Taken together, these data suggest that GSN could serve as a tumor suppressor or promoter depending on tumor type." (PMID 37958747, 2023). "GSN expression correlated with various inflammatory cells and may influence the immunity of the tumor microenvironment." (PMID 37958747, 2023). "As a biomarker in the early stage of tumor invasion and metastasis, gelsolin (GSN) might be a promising molecular target to identify and screen tumor metastasis through the lymphatic system." (PMID 36338135, 2022). "Furthermore, GSN appears to play a variety of roles in tumor biology, with evidence pointing to its involvement in tumor suppression and malignant progression." (PMID 35205837, 2022). "Hence, our results suggest that methylation of HBP1 can promote actin cytoskeleton remodeling, thus inducing growth and metastasis of tumor cells by downregulating GSN expression." (PMID 35941115, 2022). "With its versatile function, it could be hypothesized that AVIL can carry out the functions of other gelsolin/villin family proteins in tumor cells." (PMID 34948433, 2021). "ATF3 was down-regulated in BC tissues and negatively correlated with tumour stage, and could suppress BC cell metastasis through the upregulation of GSN-mediated actin remodelling." (PMID 34187252, 2021). "We suggest that the physical interaction E7/Gelsolin in HPV positive tumor cell, and the resulting epithelial to mesenchymal transition process, induce HIPPO signaling cascade by promoting YAP inactivation and favoring HPV-induced cell transformation, cancer motility and aggressiveness." (PMID 33477952, 2021). "Then, the role of GSN in tumour growth in vivo was determined by using a cancer metastasis assay." (PMID 32377190, 2020). "Although a large body of evidence suggests that Gelsolin might act as a tumor suppressor gene, its up-regulation enhances metastasis in later cancer stages." (PMID 32636728, 2020). "In contrast to Scinderin, no signification association was found between Gelsolin expression level and tumor size." (PMID 32636728, 2020). "Particularly, evaluation of extracellular gelsolin values in cancer patients is problematic, since these levels may vary during the course of tumor progression." (PMID 30149613, 2018). "However, due to a number of studies presenting opposing effects in tumor suppression versus oncogenesis, the correlation between gelsolin expression and tumorigenesis remains controversial." (PMID 30149613, 2018).